DSG2 (desmoglein 2)
Diseases named in the same sentence as DSG2 in open-access papers (continued):
Sharing a sentence is not in itself a finding about the gene and the disease.
prostate carcinoma (13 papers, 2014 to 2021). A carcinoma that arises from epithelial cells of the prostate gland. "In contrast, downregulation of Dsg2 expression has been associated with poor prognosis and increased tumor progression in diffuse-type gastric and prostate cancer." (PMID 32989241, 2021). "In primary prostate cancer patients, reduced expression of both E-cadherin and DSG2 is significantly associated with an earlier biochemical recurrence." (PMID 26033689, 2015). "We have recently reported that reduced DSG2 expression is an independent biomarker associated with a shorter BCR in prostate cancer." (PMID 26033689, 2015). "We then analyze the expression of DSG2 in a well-characterized prostate cancer patient cohort, and examine the association between DSG2 expression and patients' clinical outcome." (PMID 24896103, 2014). "Taken together, these results indicate that reduced expression of both E-cadherin and DSG2 is significantly associated with BCR in prostate cancer, but that DSG2 alone, as previously reported by our group 15 may be the most useful prognostic marker." (PMID 26033689, 2015). "Having examined the correlation between DSG2 phenotype and clinico-pathological risk factors of prostate carcinoma, we next determined whether DSG2 expression is associated with biochemical recurrence free survival." (PMID 24896103, 2014). "Low DSG2 expression has been reported in aggressive prostate cancer, squamous lung cancer and gastric cancer." (PMID 33407183, 2021). "Reduced level of DSG2 was a significant independent marker of poor clinical outcome in prostate cancer." (PMID 32095325, 2020). "In summary, these results suggest that the regulation of DSG2 expression in prostate cancer is independent from that of E-cadherin." (PMID 26033689, 2015). "The Ad5/3 D24 showed similar killing to the multi-targeting virus in cells that expressed high levels of DSG2 such as the lung and prostate cancer cell lines." (PMID 26689910, 2015). "This study aims to provide a comprehensive view of the role and regulation of cell–cell adhesion in prostate cancer aggressiveness by examining the functional implications of both E-cadherin and Desmoglein 2 (DSG2)." (PMID 26033689, 2015). "We have recently reported that reduced expression of DSG2 is an independent prognostic factor in primary prostate cancer patients." (PMID 26033689, 2015). "Next, immunofluorescence analysis was utilized to examine the expression of DSG2 in these metastatic human prostate cancer cell lines at the protein level." (PMID 24896103, 2014). "Further, reduced expression of DSG2 was found to be independently associated with a shorter biochemical recurrence, highlighting the potential utility of DSG2 expression as a prognostic biomarker of prostate cancer aggressiveness." (PMID 24896103, 2014). "A cut-off value of 60% DSG2 positive cell expression was utilized, as this was the approximate median expression value observed for DSG2 in the prostate cancer cohort, and median has been previously and widely used to perform survival analyses." (PMID 24896103, 2014). "Further analyses of DSG2 expression in prostate cancer revealed that reduced levels of this biomarker were a significant independent marker of poor clinical outcome." (PMID 24896103, 2014). "We utilized immunofluorescence to examine DSG2 expression in normal prostate (n = 50) and in a clinically well-characterized cohort of prostate cancer patients (n = 414)." (PMID 24896103, 2014). "Using this cut-off value, we observed that 96% of normal prostate tissue samples were considered positive for DSG2, in comparison to only 46% of the prostate carcinoma specimens studied." (PMID 24896103, 2014). "A significant decrease in the percentage of cells positive for DSG2 expression was found in prostate carcinomas as compared to normal prostate." (PMID 24896103, 2014). "However, DSG2 was downregulated in prostate carcinoma, pancreatic tumours, and diffuse-type gastric cancer." (PMID 32300605, 2020).
prostate carcinoma (continued). "Having found that reduced expression of E-cadherin and DSG2 are associated with BCR, we next wanted to examine the mechanisms by which E-cadherin and DSG2 expression may be reduced in prostate cancer." (PMID 26033689, 2015). "Following our previous discovery that DSG2 is expressed in normal human prostate epithelium, we then asked whether this protein is also expressed in human prostate cancer cell lines." (PMID 24896103, 2014). "The results presented in this study provide the first molecular characterization of desmoglein expression in normal human prostate, characterization of DSG2 in metastatic prostate cancer cell lines, and the first analysis of DSG2 expression in tissue samples of primary prostatic carcinoma." (PMID 24896103, 2014). "In sum, these results highlight a potentially critical role for DSG2 based cell-cell adhesion in the progression of prostate carcinoma, and demonstrate that DSG2 may be a useful predictive biomarker of clinically significant prostate cancer." (PMID 24896103, 2014). "Expression of DSG2 in prostate cancer as compared to normal prostate." (PMID 24896103, 2014). "Furthermore, DSG2 was also supposed to be an oncogene in prostate cancer." (PMID 27107420, 2016). "Additionally, the loss of E-cadherin does not result in the reciprocal loss of DSG2 in prostate cancer cells in vitro." (PMID 26033689, 2015). "Thus separate pathways may be involved in the regulation of E-cadherin and DSG2 expression in prostate cancer." (PMID 26033689, 2015). "Here we report for the first time that a low DSG2 expression phenotype is a useful prognostic biomarker of tumor aggressiveness and may serve as an aid in identifying patients with clinically significant prostate cancer." (PMID 24896103, 2014). "Interestingly, the expression of DSG2 is present in metastatic prostate cancer cell lines in vitro." (PMID 24896103, 2014). "In this study we characterized desmoglein expression in normal prostate tissues, and further investigated whether Desmoglein 2 (DSG2) expression specifically can serve as a potential clinical prognostic factor for patients diagnosed with primary prostate cancer." (PMID 24896103, 2014). "Despite encoding for a cell–cell adhesion protein, it acts independent of e-cadherin, and DSG2 is prognostic in both primary prostate cancer as well as other malignancies." (PMID 35008431, 2021). "The significance of Dsg2-Hh crosstalk has implications beyond cutaneous tumors, as both players are deregulated in a variety of cancers including oral head and neck SCC, gastric, and prostate cancers." (PMID 25871385, 2015). "In line with previous reports, we found that E-cadherin expression was significantly reduced in prostate cancer and we observed a negative correlation between the expression of both E-cadherin and DSG2 and serum PSA concentration, Gleason score, and pathological stage." (PMID 26033689, 2015). "Interestingly, the expression of DSG2 is greater in all the metastatic prostate cancer cell lines examined than it is in the non-tumorigenic BPH-1 control." (PMID 24896103, 2014). "Interestingly, DSG2 expression was significantly reduced in prostate cancer as opposed to normal prostate." (PMID 24896103, 2014).
Arrhythmia (12 papers, 2020 to 2025). Any cardiac rhythm other than the normal sinus rhythm. "Apremilast improves loss of cardiomyocyte cohesion, enhances localization of DSG2, and reduces arrhythmia in human and/or murine models of ACM ex vivo and in vitro, providing a novel treatment strategy for ACM by preserving desmosome function." (PMID 41185038, 2025). "Among these, DSG2-mutated hiPSCs-CMs were used to investigate the connection between desmosome mutations and arrhythmia." (PMID 33281612, 2020). "The few contractile-related proteins labeled by AC9 were associated with cardiac arrhythmias, including SNTA1 and desmoglein (DSG2)." (PMID 40749829, 2025). "A treatment with extracellular vesicles (EVs) in a homozygous KI mutant Dsg2 mouse decreased cardiac inflammation and arrhythmia episodes, with a global enhancement of cardiac function." (PMID 39120296, 2024). "A Dsg2-KI mouse model, eliminating the tryptophan exchange (W2A) crucial for DSG2 interactions, displayed a severe cardiac profile with arrhythmia, cardiac fibrosis and decreased systolic function." (PMID 39120296, 2024). "Testosterone, plasma bridging integrator 1, soluble ST2, miRNAs, anti-DSG2 antibodies, correlate with disease severity and arrhythmias incidence." (PMID 34206637, 2021). "Nevertheless, our data indicate that the SK4-activating effect of NDPK-B can contribute to ectopic activity and the occurrence of arrhythmias in ARVC, at least with the DSG2 mutation (p.Gly638Arg)." (PMID 32050722, 2020).
lung adenocarcinoma (11 papers, 2017 to 2026). A carcinoma that arises from the lung and is characterized by the presence of malignant glandular epithelial cells. "Both, CD109 and DSG2 are genetic risk factors, linked to reduced overall survival in lung adenocarcinoma patients (subtype of NSCLC)." (PMID 38562713, 2024). "Additionally, in lung adenocarcinoma, loss of DSG2 (via gene silencing) leads to the nuclear translocation of EGFR, as well as suppression of EGFR signaling via the Src-Rac1-PAK1 pathway." (PMID 38188287, 2023). "To date, few studies have reported that DSG2 might be an early diagnostic and independent prognostic marker for lung adenocarcinoma." (PMID 32095325, 2020). "In our study, DSG2 might be an independent risk factor for lung adenocarcinoma." (PMID 32095325, 2020). "We found a significant upregulation of DSG2 in patients with lung adenocarcinoma (LUAD), cervical squamous cell carcinoma (CESC), and pancreatic adenocarcinoma (PAAD), which negatively associates with patients’ overall survival ratio." (PMID 39813162, 2025). "Quantitative RT-PCR data, TCGA data and Oncomine datasets were utilized to validate the high expression of DSG2 in lung adenocarcinoma." (PMID 32095325, 2020). "CAR and DSG2 gene co-expression was higher in early stage lung adenocarcinoma and was shown to have a significantly poorer survival outcome, when compared with lower CAR and DSG2 gene expression (p = 0.0046)." (PMID 33217893, 2020). "DSG2 was highly expressed in lung adenocarcinoma tissues based on qRT-PCR, TCGA and Oncomine datasets." (PMID 32095325, 2020). "The expression of DSG2 protein was also higher in lung adenocarcinoma by tissue microarray and HPA database." (PMID 32095325, 2020). "Correlation between the expression of DSG2 and the clinicopathological characteristics of the lung adenocarcinoma patients." (PMID 32095325, 2020). "The molecular mechanisms of DSG2 in lung adenocarcinoma remain largely elusive and require further investigation." (PMID 32095325, 2020). "Two different antibodies (HPA004896 and CAB025122) were utilized to detect the expression of DSG2 in 9 lung adenocarcinoma tissues and 6 normal lung tissues." (PMID 32095325, 2020). "In the current study, a total of 40 paired lung adenocarcinoma samples were utilized to determine the expression of DSG2 by qRT-PCR." (PMID 32095325, 2020). "In order to explore the role of DSG2 in the development of lung adenocarcinoma, the relationship between DSG2 and the clinicopathological parameters were analyzed." (PMID 32095325, 2020). "The protein expression of DSG2 was also higher in lung adenocarcinoma." (PMID 32095325, 2020). "In this study, we have investigated the clinical value of DSG2 in lung adenocarcinoma." (PMID 32095325, 2020). "Moreover, immunostaining evidence from the Human Protein Atlas database supported the upregulation of DSG2 in lung adenocarcinoma tissues." (PMID 32095325, 2020). "However, the clinical value of DSG2 in lung adenocarcinoma remains unclear." (PMID 32095325, 2020). "Firstly, a total of 40 paired lung adenocarcinoma tissues and corresponding non-cancerous tissues were used to detect the expression of DSG2." (PMID 32095325, 2020). "Real-time reverse transcription-quantitative polymerase chain reaction (qRT-PCR) was utilized to detect the expression of DSG2 in 40 paired lung adenocarcinoma tissues and corresponding non-cancerous tissues." (PMID 32095325, 2020). "DSG2 was significantly over-expressed in lung adenocarcinoma than corresponding non-tumorous normal tissues (p < 0.001)." (PMID 32095325, 2020). "The pooled effect sizes from forest plots indicated that DSG2 was significantly highly expressed in lung adenocarcinoma than in non-cancer tissues (SMD=1.30, 95% CI [1.08–1.52], p = 0.014) using the random effect model (I2=54.8%)." (PMID 32095325, 2020).
cervical cancer (10 papers, 2020 to 2025). A primary or metastatic malignant neoplasm involving the cervix. "DSG2 expression is associated with a poor prognosis and promotes the occurrence of early cervical cancer." (PMID 38152044, 2024). "In cervical cancer, the high expression of DSG2 was associated with HPV-positive status, suggesting that DSG2 may be involved in HPV-induced cervical carcinogenesis." (PMID 34203070, 2021). "Notably, DSG2 was associated with the HPV status of cervical cancer." (PMID 32300605, 2020). "Interestingly, DSG2 was associated with the HPV status of cervical cancer." (PMID 32300605, 2020). "The poor prognosis of patients with high expression of DSG2 in cutaneous squamous cell carcinoma and cervical cancer was correlated." (PMID 37391503, 2023). "Our study constructed a prognostic model in cervical cancer and discovered two novel genes, ITM2A and DSG2, associated with cervical carcinogenesis and survival." (PMID 32300605, 2020). "In this study, the upregulation of DSG2 was observed in cervical cancer and indicated a poor outcome." (PMID 32300605, 2020). "Some other studies have shown DSG2, PLOD2, ANLN, AURKA, and AR genes might be key genes associated with cervical cancer progression." (PMID 41266827, 2025). "Qin recognized DSG2 as a biomarker which could predict the prognosis of early-stage cervical cancer." (PMID 34863153, 2021). "All cervical cancer patients with a high expression of DSG2 were HPV positive." (PMID 32300605, 2020). "DSG2 expression was not correlated with other clinicopathological parameters in cervical cancer patients." (PMID 32300605, 2020). "It is worth noting that ITM2A and DSG2 are two novel genes that have never been studied in cervical cancer." (PMID 32300605, 2020).
gastric cancer (10 papers, 2008 to 2023). A primary or metastatic malignant neoplasm involving the stomach. "Desmosomal constituents, like Dsg2, have been demonstrated to be expressed abnormally in gastric cancer and its decreased expression has been associated with poorer prognosis for diffuse-type gastric cancer." (PMID 19091121, 2008). "Finally, in gastric cancer, DSG2 was reportedly down-regulated by cell-surface glycoprotein TROP2 to promote invasion and migration through DSG2/PG/β-catenin pathways." (PMID 38188287, 2023). "Although downregulation of desmoglein-2 has been associated with gastric cancer, not much is known about abnormal proteolytic cleavage of desmosomal cadherins in the context of gastric cancer progression." (PMID 35269560, 2022). "One study identified a germline missense variant in DSG2 in a familial gastric cancer patient and no somatic mutations were identified." (PMID 32498335, 2020).
Right ventricular cardiomyopathy (9 papers, 2010 to 2025). Right ventricular dysfunction (global or regional) with functional and morphological right ventricular abnormalities, with or without left ventricular disease. "DSG2 encodes a calcium-binding transmembrane glycoprotein which has been implicated in right ventricular cardiomyopathy." (PMID 27549615, 2016). "High levels of circulating anti-DSG2 autoantibodies have been reported in recuperating COVID-19 male subjects, compared to healthy individuals, as well as a subgroup showed elevated levels compared to those in arrhythmogenic right ventricular cardiomyopathy." (PMID 36143338, 2022). "For example, mutations in JUP, DSP, PKP2, DSG2, DSC2, CTNNA3, CDH2, or PLN (all of them more abundant in LV) predominantly lead to arrhythmogenic right ventricular cardiomyopathy, and mutations in MYH7, HSPB7, NEXN and MYPN (also all more abundant in LV) lead to dilated cardiomyopathy." (PMID 32291283, 2020).